ENSG00000293630 (HOXA10-AS - HOXA11-AS readthrough transcript)
Gene: Long non-coding RNA gene on chromosome 7 (27,168,613 to 27,189,293, forward strand). Ensembl gene ENSG00000293630.
Gene Ontology:
Biological process: negative regulation of gene expression